HIF1A (hypoxia inducible factor 1 subunit alpha)
Diseases named in the same sentence as HIF1A in open-access papers (continued):
Sharing a sentence is not in itself a finding about the gene and the disease.
lung carcinoma (continued). "Our experiments demonstrated for the first time that CuB inhibits the expression of HIF-1α and reduces the proliferation, migration, invasion, and angiogenesis of lung cancer cells by inhibiting ZFP91." (PMID 40860815, 2025). "Our study demonstrated that CuB suppressed ZFP91 and HIF-1α expression in A549 cells, though their functional interplay in lung cancer remains to be elucidated." (PMID 40860815, 2025). "When HIF‐1α and glucose transporter‐1 (GLUT1) co‐localize in hypoxic conditions, lung cancer becomes more advanced, with HIF‐1α driving macrophages to polarize towards the M2 phenotype." (PMID 41190507, 2025). "EphB4 and HIF-1α play a vital role in lung cancer by promoting tumor growth, angiogenesis, and metastasis." (PMID 40011266, 2025). "In summary, this study aims to elucidate the intricate interplay between YFJDT, HIF1A, and ferroptosis in the context of lung cancer progression." (PMID 39912781, 2025). "The Journal retracts the article “Maslinic Acid Induces Mitochondrial Apoptosis and Suppresses HIF-1α Expression in A549 Lung Cancer Cells Under Normoxic and Hypoxic Conditions” cited above." (PMID 41289053, 2025). "Collectively, these results support that hypoxia signaling is a generalizable marker of lung cancer in the LC-iCAP and suggest the involvement of HIF1A and HIF2A in the response observed in the indicator cells." (PMID 40831733, 2025). "The possible linkage between ACE2 and HIF1α in lung cancer is a new discovery, and has only been suggested in two previous studies." (PMID 39273283, 2024). "These increased levels of ROS and succinate downregulated the protein expression level of PHD2 and increased the level of HIF-1α in lung cancer cells." (PMID 38880883, 2024). "For further confirmation, we transfected miR‐210‐3p mimic in HIF‐1A silenced lung cancer cells, and HIF‐1A overexpressed lung cancer cells were transfected with the miR‐210‐3p inhibitor." (PMID 35658112, 2024). "Molecular docking assessments revealed pronounced affinity between 6-alpha-diol and HIF1A, underscoring their potential as therapeutic agents for lung cancer." (PMID 39113883, 2024). "Herein we showed that LUBAC increases HIF1α protein expression in cultured cells and tissues of human lung cancer and enhances HIF1α DNA-binding and transcriptional activities, which are dependent upon LUBAC enzymatic activity." (PMID 38272870, 2024). "Our work also sheds new light on the mechanism underlying LUBAC in regulating HIF1α homeostasis, tumor angiogenesis and lung tumorigenesis, making LUBAC an attractive therapeutic target for lung carcinoma." (PMID 38272870, 2024). "This work provides novel mechanistic insights into the role of LUBAC in regulating HIF1α homeostasis, tumor angiogenesis and tumorigenesis of lung cancer, making LUBAC an attractive therapeutic target for cancers." (PMID 38272870, 2024). "Ropivacaine, a local anesthetic, has been shown to inhibit HIF-1α signaling in lung cancer cells, along with downstream VEGF signaling, thus reducing angiogenesis in malignant lung cancers." (PMID 39737184, 2024). "This discovery further underscores the crucial role HIF-1α plays in the occurrence and development of lung cancer, and its importance cannot be overlooked." (PMID 39236027, 2024). "Among the 5-lung cancer associated genes, HSP90AA1 and HIF1A were highly expressed in LUAD and LUSC datasets." (PMID 39113883, 2024). "It has been reported that the activation of the AKT/HIF-1α signaling pathway by WDR72 can lead to an increase in the stem-like properties of lung cancer stem cells." (PMID 39268080, 2024). "Previous research has proposed the presence of an miR-622 sequence complementary to the 3′-untranslated region (3′-UTR) of HIF-1α in lung cancer cells." (PMID 38339408, 2024). "Unlike traditional 2D cell cultures, VEGF gene expression was found to be regulated by HIF-1α in lung cancer 3D models, similar to what is observed in vivo." (PMID 39376603, 2024).
lung carcinoma (continued). "In particular, 6-alpha-diol has the potential to modulate HIF1A signaling in hypoxic environments relevant to lung cancer, thereby influencing processes, such as angiogenesis, metabolism, and cell survival." (PMID 39113883, 2024). "Knockout of CAMSAP3 promoted invasion and malignant progression of lung cancer and the expression of HIF-1α." (PMID 38880903, 2024). "We found that HOIP expression was elevated in lung cancers compared with the adjacent normal tissues, which was correlated with HIF1α expression." (PMID 38272870, 2024). "More notably, multiple pieces of evidence suggest that the expression level of HIF-1α is significantly correlated with the prognosis of lung cancer patients." (PMID 39236027, 2024). "We further validated HIF-1α protein expression in lung cancer patients and observed a higher HIF-1α expression level in tumor tissue than in normal tissue." (PMID 38609977, 2024). "6-Gingerol has been reported to suppress the expression of HIF-1α and reduce hypoxia in lung cancer." (PMID 39033184, 2024). "This indicates that the HIF-1α/miR-101/EZH2 network is active even under normal O2 circumstances in lung cancer cells (HCC4006, HCC461, and HCC1171) that are subjected to increased VEGF stimulation and high levels of VEGFR-2 expression." (PMID 38911968, 2024). "LUBAC also boosts angiogenesis and exacerbates lung cancer growth in mice, which are greatly compromised by inhibition of HIF1α." (PMID 38272870, 2024). "K8 lysates markedly downregulated hypoxia-induced HIF1α accumulation in the human bone marrow and lung cancer cell lines, SH-SY5Y and H460." (PMID 38491188, 2024). "The hypoxic environment of lung cancer provokes the expression of hypoxia-inducible factor 1-alpha (HIF-1α) in fibroblasts and facilitates their transformation to CAFs." (PMID 39403603, 2024). "In myeloid-derived suppressor cells (MDSCs) of LLC (Lewis Lung Carcinoma) mice, HIF-1α can directly bind to the hypoxia-response element (HRE) in the CD274 promoter, promoting PD-L1 transcription." (PMID 38426097, 2024). "This is evident in cancers like glioblastoma, hepatocarcinoma, and lung cancer, where HIF1α enhances DNA repair, contributing to resistance against therapies." (PMID 39697237, 2024). "HIF1α expression in clinicopathological samples is well known as a poor prognostic factor in many types of human cancers, including lung cancer." (PMID 39273283, 2024). "Our previous study found that incomplete RFA increased the proliferation of residual lung cancer cells via the HSP70/HIF-1α axis." (PMID 37948404, 2023). "The tumor slices of H1437 xenografts, a lung cancer model, were stained for Ki67, HIF1α, γH2AX, and cleaved-caspase 3 (CC3) to investigate cell proliferation, oxygen supply, DNA damage and apoptosis." (PMID 36899943, 2023). "HIF1α staining of tumor samples from the melanoma and lung cancer models showed that JP1 significantly improved the intratumor microenvironment hypoxia." (PMID 37192004, 2023). "HIF-1α is overexpressed in several cancers, such as colon, kidney, pancreas, esophagus, endometrial, prostate, breast, stomach, and lung cancers." (PMID 37445752, 2023). "We found that PRMT5 positively correlated with HIF-1α and PI3K/Akt signaling pathway in lung cancer, suggesting a potential association between these genes and pathways." (PMID 37400960, 2023). "AK4 overexpression promotes lung cancer metastasis by enhancing HIF-1α stability and epithelial–mesenchymal transition (EMT) under hypoxic conditions." (PMID 36982634, 2023). "A novel signaling cascade, IL-6/STAT3/HIF-1α, has been discovered in numerous cancer types including pancreatic cancer, prostate cancer, lung cancer, colon cancer, and malignant glioma." (PMID 36814597, 2023). "Sevoflurane has also been shown to suppress A549 lung cancer cell proliferation by regulating the relevant anti-cancer signaling pathway, such as matrix metalloproteinase and HIF-1α." (PMID 36984614, 2023).
lung carcinoma (continued). "Elucidating the regulatory effect of the HIF-1α pathway on lung cancer recurrence after radiofrequency ablation is of great importance for improving the prognosis of NSCLC patients." (PMID 37948404, 2023). "Overexpression of HIF-1α in lung tumour cells is associated with higher invasiveness and metastasis, and HIF-1α is considered to be a biomarker of poor prognosis in human lung cancer." (PMID 37841777, 2023). "Under RFA therapy, lung cancer cells have been shown to transform into a proliferative heat-tolerant subtype and result in high HIF-1α expression." (PMID 37948404, 2023). "COVID-19 can induce hypoxemia and overexpression of hypoxia-inducible factor-1α (HIF-1α), which is involved in the genesis, angiogenesis, invasion and metastasis of lung cancer." (PMID 37063865, 2023). "Evidence suggests that HIF1A drives tumor progression via regulating glycolysis, angiogenesis, and cell cycle progression in lung cancer." (PMID 38180107, 2023). "Tetrandrine (Tet) can inhibit lung cancer cell proliferation, induce apoptosis, and suppress lung cancer growth by destructing the VEGF/HIF-1α/ICAM-1 signaling pathway." (PMID 38136352, 2023). "Studies showed that patients with lung cancer and high HIF-1α expression have a significantly shorter overall survival (OS) and that high HIF-1α expression is also associated with tumor metastasis and a higher Eastern Cooperative Oncology Group (ECOG) rating." (PMID 37445752, 2023). "Knockdown NARFL was reported to increase HIF-1α expression, and our results presented that HIF-1α was also upregulated caused by NARFL knockdown in lung cancer cell lines." (PMID 37821486, 2023). "In summary, HSP70, via HIF-1α SUMOylation, inhibited ferroptosis, inducing lung cancer recurrence after radiofrequency ablation." (PMID 37948404, 2023). "In summary, the present in vivo and in vitro study delineates FD-induced and mTORC1/AMPK//HIF-1α-signaling-mediated lactate metabolism disorders in lung cancer metastasis." (PMID 36986244, 2023). "There is a significant correlation between HIF1A and lung cancer, and the expression of HIF1A in non-small cell lung cancer is mediated by the AKT and ERK signaling pathways." (PMID 36937508, 2023). "The transcriptional factor HIF-1α plays a crucial role in the development of many tumor types, including breast, colonic, and lung cancer while the cellular signaling Erk1/2 pathway can regulate HIF-1α." (PMID 36207479, 2023). "miR-23a directly inhibits its targets, prolyl hydroxylases 1 and 2 (PHD1 and 2), in exosomes from lung cancer cells, resulting in the accumulation of hypoxia-inducible factor 1 alpha (HIF-1α) in endothelial cells." (PMID 37602326, 2023). "Hypoxia-inducible factor (HIF-1α) is a therapeutic target in lung cancer that monitors how cells respond to oxygen levels in solid tumors." (PMID 37747648, 2023). "This was also observed in LKB1 mutant lung cancer in a process supported by mTORC1-dependent Hypoxia-inducible factor 1-alpha (HIF1a) expression." (PMID 37180110, 2023). "We showed that inhibition of EGFR by gefitinib reduced hypoxia-induced HIF-1α expression, compatible with the previous report showing a decrease in hypoxia-induced accumulation of HIF-1α after EGFR inhibition in human lung cancer A549 cells." (PMID 35634326, 2022). "The sphere formation of lung cancer stem cells was significantly diminished after inhibiting the AKT/HIF-1α pathway." (PMID 36385964, 2022). "Downregulating IDH2 leads to increased α-KG and consequently decreased HIF-1α expression, reducing lung cancer cell proliferation and promoting cellular glucose uptake and lactate production." (PMID 36497259, 2022). "A study suggested that miR-28-5p suppressed the cell growth, invasion, and migration of NSCLC by targeting HIF-1α and inducing apoptosis in lung cancer cells." (PMID 35873635, 2022).
lung carcinoma (continued). "The expressions of C/EBPα and PPARγ were upregulated in several cell lines, and SREPB1, HIF-1α, PPARα, and PPARβ were more widely overexpressed in lung cancer cells." (PMID 36293388, 2022). "Panobinostat caused apoptosis mediated by chromatin fragmentation, the activation of caspases-3 and 7, and PARP via HIF-1α destabilization in cisplatin-resistant lung cancer cells." (PMID 36551540, 2022). "Immunohistochemical (IHC) staining results showed that the HIF-1α protein levels in cancerous tissues (Ca) from lung cancer patients were higher than those in paracancerous tissues (Para-Ca)." (PMID 36531060, 2022). "WDR72 activates the AKT/HIF-1α signaling pathway to enhance the stemness of lung cancer stem cells and promote the growth and metastasis of lung cancer." (PMID 36385964, 2022). "In contrast, lncRNA TSLNC8 suppresses migration effects on lung cancer cells by regulating HIF1A signaling." (PMID 36230902, 2022). "HIF-1α levels in lung cancer tissue samples are excessively high and play a crucial role in tumor genesis, development, and metastasis." (PMID 36338690, 2022). "Increasing studies have highlighted the importance of both the AhR and HIF-1α signaling pathways in the development of lung cancer." (PMID 35473600, 2022). "Taken together, miR-326 represses SIRT1 through impeding HIF1α expression, thus hindering chemotherapy resistance in lung cancer." (PMID 34696659, 2022). "In this review, we discuss the molecular aspects of the crosstalk between hypoxia and inflammation, showing that HIF-1α is an important signaling pathway that drives COPD progression to lung cancer." (PMID 36338690, 2022). "Multiple studies have indicated that the activation and expression levels of HIF-1α are closely correlated with the outcome of lung cancer." (PMID 35918758, 2022). "Using in vitro IH cell model, we further confirmed that EVs derived from intermittent hypoxic lung cancer cells upregulated PD-L1 in macrophages through HIF-1α pathway." (PMID 34254261, 2022). "Taken together, WDR72 can regulate the AKT/HIF-1α signaling pathway to enhance the stemness of LCSCs and promote the growth and metastasis of lung cancer, but its application in clinical diagnosis and treatment needs to be researched further." (PMID 36385964, 2022). "Modulating the expression of HIF1α by siRNA (downregulating HIF1α expression) or cobalt chloride (inducing hypoxia and HIF1α upregulation) markedly reduces or increases the transcription of XPA in lung cancer cell lines, respectively." (PMID 36496984, 2022). "FOXM1, a member of the Forkhead box (FOX) family of transcription factors, was reported to be transcriptionally regulated by HIF1α under hypoxic conditions and overexpressed in many types of cancers including liver cancer, breast cancer, and lung cancer." (PMID 35365182, 2022). "As a high-affinity membrane receptor, CD74 is involved in multiple signaling pathways mediated by macrophage migration inhibitor (MIF), including promoting the Warburg effect by activating the NF-κB/HIF-1α pathway in lung cancer." (PMID 36358600, 2022). "We have previously shown that HIF-1α is essential for the activation of CAFs in lung cancer 8, and we showed here its ability to promote the accumulation of LDs in CAFs." (PMID 36439884, 2022). "Analysis of human lung adenocarcinoma tissue chip revealed that CAFs with a high level of SCD1 were positively correlated with the expression of HIF-1α and poor survival in lung cancer patients." (PMID 36439884, 2022). "HIF-1α signaling plays a key role in the progression of COPD to lung cancer and is a potential therapeutic target to delay the progression." (PMID 36338690, 2022). "Collectively, miR-449a depressed KDM3A to incur tumor activities in lung cancer through down-regulating HIF-1α." (PMID 34044859, 2021). "EZH2 activity correlated with PD-L1 downregulation in hepatocarcinoma and was dependent on the HIF-1α (hypoxia-inducible factor 1 alpha) activation in lung cancer." (PMID 34503236, 2021).
lung carcinoma (continued). "Apoptosis of lung cancer cells is suppressed by Tet treatment through the VEGF/HIF-1α/ICAM-1 pathway." (PMID 33763489, 2021). "Here, we demonstrated that hypoxia suppresses miR101 levels in lung cancer cells and derived exosomes, which was modulated by HIF1α." (PMID 34362882, 2021). "HIF-1α regulates the secretion of HSP90α, while hypoxia inducible factor-1 (HIF-1α) is a significant regulator of PD-L1 mRNA and protein expression in lung cancer." (PMID 34926266, 2021). "Increased HIF-1α stability explains the increased expression in high grade lung cancer cells that supports invasion and growth and plays a role in the increased glycolytic ability in cancer cells." (PMID 33916349, 2021). "A COPD-like inflammation supported a tumourigenic effect of KRAS mutant lung cancer, driven by HIF-1α." (PMID 34298636, 2021). "MiR-200c was found to inversely regulate the HIF1α expression level on protein and the mRNA level in lung cancer." (PMID 33916349, 2021). "Tetrandrine consequently reduces and increases the level of VEGF and BCL2-associated X protein (BAX), respectively, denoting the involvement of HIF-1α in the anti-angiogenic and apoptosis effects of tetrandrine in lung cancer." (PMID 34575983, 2021). "Another study demonstrated that radio-resistance of HIF-1α-overexpressing lung cancer cells is weakened by ursolic acid treatment." (PMID 34575983, 2021). "Micheliolide also sensitizes lung cancer cells to irradiation, owing to its prohibitory action on HIF-1α." (PMID 34575983, 2021). "miR-449a, KDM3A and HIF-1α levels in lung cancer tissues and cell lines (A549, H1299 and H460) were measured." (PMID 34044859, 2021). "Taken together, our results suggest that Huaier inhibits the proliferation, migration and energy metabolism of human lung cancer A549 cells through regulating PI3K/AKT/HIF‐1α pathway." (PMID 33377619, 2021). "In lung cancer, the underlying mechanisms by which AK4 drives metastasis include the stabilization of HIF-1α and inhibition of AMPK." (PMID 34638712, 2021). "Then, it was revealed that restoring KDM3A or HIF-1α negated overexpressed miR-449a-induced effects on cellular growth in lung cancer." (PMID 34044859, 2021). "Our data demonstrated a new mechanism by which echinomycin simultaneously targets MYC and HIF1α for degradation to inhibit growth of lung cancer and lymphoma." (PMID 33572152, 2021). "Recently, it was demonstrated that cephalomannine inhibits the interaction of APEX1 and HIF-1α, resulting in the attenuation of cell viability and migration of lung cancer cells under hypoxic conditions." (PMID 34575983, 2021). "HIF-1α is stable under low oxygen tension, so in our experiment, lung cancer cells were treated with cobalt chloride to obtain a hypoxic environment, and as a result, HIF-1α was upregulated in A549 and H1299 cells but decreased by ropivacaine in our study." (PMID 35280249, 2021). "Overexpression of MIF also activates NF‐κB and further upregulates HIF‐1α, thus amplifying proliferation and Warburg effect in lung cancer." (PMID 33314730, 2021). "Most importantly, the morphology and distribution of fibroblasts in the tissues can be used to observe the expression of HIF‐1α in the fibroblast of lung cancer tissues and normal lung tissues." (PMID 33943003, 2021). "The stability of HIF-1α has been recognized to modulate the stem-like characteristics of lung cancer cells, as well as drug resistance and tumor progression in lung cancer." (PMID 34044859, 2021). "In lung cancer, activated HIF1α is a transcription factor that transactivates ALDOA and promotes the Warburg effect, increasing lactate production under hypoxia." (PMID 35008539, 2021). "We then repeated the validation analysis with other two target genes, HIF1A and ERBB3, both of which have expressions associated with lung cancer progress and prognosis." (PMID 34422018, 2021).